RNU6-1111P (RNA, U6 small nuclear 1111, pseudogene)
Gene: Small nuclear RNA gene on chromosome 15 (89,886,485 to 89,886,591, reverse strand). Ensembl gene ENSG00000212420.
Homologues: Orthologues: chimpanzee U6 (99% identical), macaque U6 (93% identical), guinea pig U6 (83% identical). Paralogues in human: RNU6-1251P (83% identical), RNU6-242P (83% identical), RNU6-41P (83% identical), RNU6-1029P (82% identical), RNU6-48P (82% identical), RNU6-73P (82% identical), RNU6-1011P (81% identical), RNU6-1117P (81% identical), RNU6-1230P (81% identical), RNU6-12P (81% identical), RNU6-13P (81% identical), RNU6-140P (81% identical), and 1287 more.